ENTPD1 (ectonucleoside triphosphate diphosphohydrolase 1)
Description:
Catalyzes the hydrolysis of nucleoside triphosphates (NTPs) and diphosphates (NDPs) (Probable). The enzyme sequentially removes phosphate groups in two successive steps, converting NTPs to nucleoside monophosphates (NMPs) via NDP intermediates (Probable). This activity contributes to the regulation of extracellular levels of nucleotides (Probable). By hydrolyzing proinflammatory ATP and platelet-activating ADP to AMP, it blocks platelet aggregation and supports blood flow.
Synonyms: ATP-DPH; ATPDase; CD39; NTPDase-1; SPG64
Tractability: Small molecule: a high-quality ligand is known. Antibody: its Gene Ontology location is reachable by antibodies, with high confidence; UniProt predicts a signal peptide or a membrane-spanning region. PROTAC: its protein half-life has been measured; a small molecule that binds it is known.
Target class: Enzyme; Hydrolase
Gene: Protein-coding gene on chromosome 10 (95,711,779 to 95,877,266, forward strand). Ensembl gene ENSG00000138185.
Subcellular location: Membrane; Membrane, caveola
Subcellular location (Human Protein Atlas): Microtubules
Pathways (Reactome):
Disease: Purinergic signaling in leishmaniasis infection
Metabolism: Phosphate bond hydrolysis by NTPDase proteins
Gene Ontology:
Molecular function: ADP phosphatase activity; apyrase activity; ATP hydrolysis activity; CTPase activity; GDP phosphatase activity; GTPase activity; IDP phosphatase activity; ITPase activity; nucleoside diphosphate phosphatase activity; protein binding; ribonucleoside triphosphate phosphatase activity; UDP phosphatase activity; CDP phosphatase activity; hydrolase activity; pyrophosphatase activity
Biological process: platelet aggregation; blood coagulation; cell adhesion; nucleoside diphosphate catabolic process; ADP catabolic process
Cellular component: caveola; extracellular exosome; membrane; plasma membrane; basement membrane; external side of plasma membrane
Genetic constraint (gnomAD): Loss-of-function variants: 33 observed, 59.84 expected, observed/expected ratio (o/e) 0.55, 90% interval 0.42 to 0.74. The upper end of that interval is the gene's LOEUF score, 0.74, which puts it in group 3 of 6, group 1 being the genes least tolerant of losing a copy. Missense variants: 501 observed, 634.62 expected, observed/expected ratio (o/e) 0.79, 90% interval 0.73 to 0.85. Synonymous variants: 202 observed, 231.81 expected, observed/expected ratio (o/e) 0.87, 90% interval 0.78 to 0.98.
Gene-disease validity (ClinGen):
ClinGen rates the evidence that ENTPD1 causes each of these diseases.
complex hereditary spastic paraplegia (autosomal recessive): Definitive. A hereditary spastic paraplegia that is part of a larger syndrome.
Homologues: Orthologues: chimpanzee ENTPD1 (99% identical), macaque ENTPD1 (97% identical), dog ENTPD1 (76% identical), mouse Entpd1 (75% identical), rabbit ENTPD1 (75% identical), rat Entpd1 (74% identical), guinea pig ENTPD1 (74% identical), pig ENTPD1 (71% identical), tropical clawed frog entpd1 (56% identical), zebrafish entpd1 (51% identical). Paralogues in human: ENTPD8 (41% identical), ENTPD2 (38% identical), ENTPD3 (36% identical), ENTPD4 (25% identical), ENTPD7 (24% identical), ENTPD5 (21% identical), ENTPD6 (19% identical).
Diseases named in the same sentence as ENTPD1 in open-access papers:
ENTPD1 is named in the same sentence as 317 diseases in open-access papers, as found by Europe PMC text mining. Sharing a sentence is not in itself a finding about the gene and the disease. The quoted sentences say what the papers report.
melanoma (79 papers, 2007 to 2026). A malignant, usually aggressive tumor composed of atypical, neoplastic melanocytes. "CD39 is mainly a (FOXP3 +) Treg marker; in fact in melanoma and colon cancer models, ENTPD1-deficient mice displayed impaired Treg-suppressive functions." (PMID 37142825, 2024). "In both mouse and human melanoma tumors we observed that Tcf7+ Pdcd1+ Tpe were enriched in Slamf6 and depleted of Havcr2 and Entpd1, which encode Slamf6, Tim3, and CD39 cell surface proteins, respectively." (PMID 32174925, 2020). "Entpd1-deficient mice that were administered B16-F10 mouse melanoma cells and MC-38 mouse colon cancer cells via the hepatic portal vein (experimental metastasis assay) were found to develop significantly fewer hepatic metastases than wildtype (control) mice." (PMID 32245826, 2020). "Transcriptomic analysis of Tpe vs. Tex CD8 TIL subsets from B16 tumors and primary human melanoma tumors revealed that Tpes are enriched in Slamf6 and lack Entpd1 and Havcr2 expression, which encode Slamf6, CD39, and Tim3 cell surface proteins, respectively." (PMID 32174925, 2020). "The present study demonstrated that inhibiting ENTPD1 can enhance the anticancer efficacy of ceritinib in triple negative breast cancer, melanoma cells, and non‐small cell lung cancer." (PMID 40360443, 2025). "Inhibition of ENTPD1 by small molecular inhibitor polyoxometalate-1 or Entpd1 deletion blocked the metastasis of melanoma and colon cancer cells." (PMID 37190251, 2023). "Dysfunctional CD8+ T cells are characterised by expressing different inhibitory molecules, such as LAG3, PDCD1 (encoding PD-1), CXCL13, HAVCR2 (encoding Tim3), ENTPD1 (encoding CD39), CTLA4, and TIGIT, which are all less expressed in memory-like T cells in melanoma." (PMID 38893071, 2024). "However, among Pdcd1+ Tim3– Slamf6+ cells we found heterogeneous expression of Entpd1, a marker of Tex, both in murine and human melanoma tumors." (PMID 32174925, 2020). "Like melanoma, MANA-specific TIL in NSCLC showed higher expression of CXCL13 and ENTPD1, and lower expression of IL7R compared with virus-specific TIL." (PMID 39900903, 2025). "In this study, we screened a human miRNA library and identified miRNAs affecting the expression of ICMs NT5E, ENTPD1, and CD274 in the human tumor cell lines SK-Mel-28 (melanoma) and MDA-MB-231 (breast cancer)." (PMID 37409119, 2023). "A number of identified molecules including TNFRSF13B, LAG3, NRP1, ENTPD1, NT5E, CCL21, and CCR7 can serve as future therapeutic targets in melanoma treatment." (PMID 34159752, 2021). "A number of identified molecules, including TNFRSF13B, LAG3, NRP1, ENTPD1, NT5E, CCL21, and CCR7, can serve as future therapeutic targets in the treatment of melanoma." (PMID 34159752, 2021). "Importantly, the majority of MANA-specific TIL resided in similar TRM clusters in both cancers (84.62% for NSCLC and 59.78% for melanoma), characterized by expression of CD103, CXCL13, ZNF683, and ENTPD1 (CD39)." (PMID 39900903, 2025). "Here authors show that mutation-associated neoantigen-specific CD8+ tumor-infiltrating lymphocytes can be recognized by MANAscore, an algorithm that uses weighted expression levels of CXCL13, ENTPD1 and IL7R in single-cell RNAseq datasets of lung cancer and melanoma patients as input." (PMID 39900903, 2025). "Based on these results, the role of CD39/ ENTPD1 in the negative effect of a high NLR on the oncologic outcomes of patients with advanced melanoma can be speculated." (PMID 37684649, 2023).
COVID-19 (39 papers, 2020 to 2025). A disease caused by infection with severe acute respiratory syndrome coronavirus 2. "We observed significant upregulation of CD39 (ENTPD1) and CD73 (NT5E), which was confirmed by immunohistochemical experiments, both of which are able to hydrolyze ATP, in SCTs of the COVID-19 group." (PMID 38441496, 2024). "Meanwhile, the correlation analysis of ICD-related DEGs and immune cell infiltration in severe COVID-19 showed that TLR4, PIK3CA, FOXP3, ENTPD1, CD4, CASP1 and BAX were significantly correlated with a variety of immune cell infiltration." (PMID 38600309, 2024). "This is in opposition to the previous literature, which noted ENTPD1 as a key mediator of the purinergic pathway in the form of ENTPD1/CD39, an ectonucleotide enzyme that scavenges pro-inflammatory ATP and ADP into AMP in critically ill COVID-19 patients." (PMID 36979757, 2023). "Herein, we detected the gene expression of ENPP1, ENPP2, ENPP3, ENTPD1 (CD39), ENTPD5, and NT5E (CD73) in the whole blood of COVID-19 patients." (PMID 36248842, 2022). "However, it increased expression levels of alarmins S100A12 and S100A9, and it decreased the expression of MHCII and ENTPD1 of CD14+ monocytes, suggesting that persistent levels of SPP1 may contribute to long–COVID-19 pathologies by skewing monocytes toward a proinflammatory phenotype." (PMID 34143756, 2021).
colorectal cancer (38 papers, 2016 to 2025). A primary or metastatic malignant neoplasm that affects the colon or rectum. "This subpopulation was significantly different from the transition-state CD8+ Texint cells, characterized by high Cx3cr1 expression, and terminally exhausted CD8+ Texterm cells, which highly expressed Entpd1 and Havcr2 in colorectal cancer; it was in line with the results of related studies." (PMID 40236705, 2025). "AGPAT4, ENTPD1, HADHB, CA12, CA9 was reported in colorectal cancer." (PMID 33815132, 2021).
breast cancer (37 papers, 2017 to 2025). A primary or metastatic malignant neoplasm involving the breast. "In primary ER+ breast cancer, high levels of the triplet ENTPD1/NT5E/ADORA3 expression signature was correlated with lower overall, distant metastasis-free, and progression-free survival." (PMID 36186774, 2022). "PANX1 expression was also positively correlated with tumor-associated neutrophil (TAN) infiltration in breast cancer TME and TANs highly expressed ENTPD1 (CD39)/NT5E (CD73)." (PMID 35884429, 2022). "What was noteworthy was that ENTPD1/CD39 (ectonucleoside triphosphate diphosphohydrolase 1) encodes a plasma membrane protein that hydrolyzes high-energy phosphate bonds, and some regulatory T cells with ENTPD1/CD39 overexpression played an important role in the breast cancer microenvironment." (PMID 33815132, 2021). "ENTPD1, NT5E, and ADORA3 showed higher expression in bone metastases than in primary breast cancers,top, GSE47561." (PMID 36186774, 2022). "Our study demonstrated that ENTPD1 and NT5E expressions were higher in the PANX1 high expression basal-like breast cancer and PANX1 upregulated exADO levels in the TME." (PMID 35884429, 2022). "TANs could highly express ENTPD1/NT5E, which synergistically contributes to an immunosuppressive environment with high exADO levels in basal-like breast cancer." (PMID 35884429, 2022). "The RNA-seq data of surgical breast cancer specimens (basal-like PANX1 high: n = 6; basal-like PANX1 low: n = 6; Luminal subtype: n = 3) suggested a higher expression of ENTPD1 and NT5E in the basal-like PANX1-high group compared to basal-like PANX1-low and Luminal group (p < 0.05)." (PMID 35884429, 2022). "The ENTPD1/NT5E/ADORA3 expression signature was not correlated with either outcome in ER–, HER2-enriched, or basal breast cancers, which do not share the same metastatic behavior, nor were signatures combining expression of the ectonucleotidases with any of the other aADO receptors in ER+ tumors." (PMID 36186774, 2022).
colitis (36 papers, 2015 to 2026). Inflammation of the colon. "In colonic CD8+ T cells from pediatric cases of colitis, decreased ENTPD1 expression was observed in association with a defective cyclic AMP (cAMP) pathway." (PMID 38179052, 2023). "Global Entpd1/Cd39 deletion in dextran-sulfate-sodium (DSS)-induced colitis in mice increases susceptibility to injury." (PMID 30941139, 2019). "ENTPD1 KO mice have a high susceptibility to murine colitis." (PMID 35730568, 2022). "As a result, they demonstrated increased expression of Entpd1 and elevated cAMP levels also influenced platelet aggregation and TNFα production, linking the findings observed in a pre-clinical model of colitis back to human IBD." (PMID 38179052, 2023). "Immune phenotyping of IELs showed that the proportion of resident CD8+ T cells expressing ENTPD1 (CD39) and γδT cells is significantly decreased in the colonic mucosa of children with colitis and IBD." (PMID 32386055, 2020). "In the context of DSS colitis, ENTPD1/CD39 and CD73 expression on activated macrophages was found to limit inflammation, either by directly hydrolyzing pro-inflammatory extracellular ATP into adenosine or by indirectly promoting Treg development." (PMID 33072065, 2020). "We have also noted that UCB treatment ameliorates DSS colitis in mice, this protective effect being dependent on ENTPD1/CD39 and AhR." (PMID 30941139, 2019). "In mice, CD39/ENTPD1 deletion exacerbates dextran-sulfate-sodium (DSS)-induced experimental colitis." (PMID 30691212, 2019). "In previous studies, administration of apyrase, which has ectoenzymatic activity comparable to CD39, strongly ameliorated DSS colitis in ENTPD1/CD39−/− mice." (PMID 30691212, 2019). "Interestingly, the ectoenzyme ENTPD1, which was shown to protect from intestinal injury in colitis, was found to be strongly expressed in in vitro ILC3 whereas it was weak in tonsillar ILC3, CB ILC3-like, and DN cells." (PMID 35003122, 2021).
ovarian carcinoma (33 papers, 2014 to 2025). A malignant neoplasm originating from the surface ovarian epithelium. "In ovarian cancer, neutrophil-derived IL-27 maintains the immunosuppressive phenotype of tumor-associated macrophages, by increasing ectonucleoside triphosphate diphosphohydrolase-1 (ENTPD1)/CD39 and PD-L1 expression, and IL-10 production." (PMID 32143355, 2020). "Using the R2 database, gene expression data from 285 ovarian cancer tissues from the AOCS (Australian Ovarian Cancer Study) were screened for genes correlating with the presence of CD39 (ENTPD1(209473_at)) or, respectively, CD73." (PMID 27532024, 2016). "In ovarian cancer, high levels of adenosine are due to tumor-specific expression of the ectonucleotidases CD39/ENTPD1 and CD73/ecto-5′-nucleotidase which synergistically catalyze the degradation of extracellular immune-stimulatory ATP to immune-inhibitory adenosine." (PMID 27532024, 2016).
glioma (29 papers, 2017 to 2025). A benign or malignant brain and spinal cord tumor that arises from glial cells (astrocytes, oligodendrocytes, ependymal cells). "Elevated expression of ENTPD1 has been associated with poor prognosis in multiple cancers, including gliomas, where it promotes T cell exhaustion and supports the expansion of regulatory T cells (Tregs)." (PMID 40636690, 2025). "Additionally, our results identified specific immune-related molecules—TNFSF4, HLA-DRA, and ENTPD1—that were significantly correlated with the crotonylation-associated risk score, further linking crotonylation pathways to the regulation of the immune microenvironment in gliomas." (PMID 40636690, 2025). "Here, through the analysis of 11 commonly studied checkpoint and inhibitory receptors, we discern that only HAVCR2 (TIM3) and ENTPD1 (CD39) display significantly greater gene expression in glioblastoma compared to normal brain and lower grade glioma." (PMID 39513882, 2024).
Sepsis (29 papers, 2012 to 2026). Sepsis is defined as life-threatening organ dysfunction caused by a dysregulated host response to infection. "Those four studies have emphasized the protective role of ENTPD1 in sepsis, thus providing strong evidence that ENTPD1 is a susceptibility gene for severe burn patients complicated with sepsis." (PMID 36659877, 2023). "ENTPD1 alleviates sepsis-associated liver injury by eliminating Extracellular adenosine triphosphate (eATP)." (PMID 36659877, 2023). "We identified ENTPD1 as one of the hub genes of sepsis, in accordance with a study that shows that ENTPD1 increases extracellular ATP metabolism, inhibits inflammatory signaling, and attenuates sepsis-associated liver injury." (PMID 35265105, 2022). "Meanwhile, the present study identified eight metabolism-related genes (NME1, NME6, POLD4, POLE4, POLR2J, POLR2L, ADCY3, and ENTPD1) in patients with sepsis and the identified metabolism-related genes may represent diagnostic and therapeutic biomarkers of sepsis." (PMID 35265105, 2022). "In the present study, mutations in ENTPD1, ZFAND4, DNAH11 and LAMA2 increased the risk of comorbid sepsis in severely burned patients." (PMID 36659877, 2023). "Through genomic analysis, we identified seven important susceptibility genes (DNAH11, LAMA2, ABCA2, ZFAND4, CEP290, MUC20 and ENTPD1) in patients with severe burn injuries complicated with sepsis." (PMID 36659877, 2023). "The DNAH11, ZFAND4, LAMA2 and ENTPD1 genes have been shown to have protective effects against sepsis." (PMID 36659877, 2023). "At the genetic level, seven susceptibility genes for sepsis in severe burn patients were found: DNAH11, LAMA2, ABCA2, ZFAND4, CEP290, MUC20 and ENTPD1." (PMID 36659877, 2023). "Notably, the dendritic cell population expressed differentiated levels of the ENTPD1 gene in bacterial induced sepsis." (PMID 36979757, 2023).
colon carcinoma (28 papers, 2013 to 2025). "Taken together, this suggests that frequencies of CD39+ Treg in peripheral blood, as well as the ENTPD1 SNPs of each patient may serve as biomarkers to assess the corresponding CD39+ Treg frequencies in colon tumors." (PMID 34407765, 2021).
autoimmune disease (26 papers, 2012 to 2026). A disorder resulting from loss of function or tissue destruction of an organ or multiple organs, arising from humoral or cellular immune responses of the individual to their own tissue constituents. "Moreover, they showed that GMSCs not only express ENTPD1 but also enhance the frequency of ENTPD1+Foxp3+ Tregs—a unique type of cells with a regulatory function in the autoimmune disease model." (PMID 37895880, 2023).
viral infections (23 papers, 2012 to 2025). "The overall transcriptional signature we observe is a broad one, with an induction of ISGs (not unexpected in a context of viral infection), but also of cell proliferation, and of heightened effector functions (ENTPD1, LAG3, LRRC32)." (PMID 34433692, 2021).